TRAF2 (TNF receptor associated factor 2)
Diseases named in the same sentence as TRAF2 in open-access papers (continued):
Sharing a sentence is not in itself a finding about the gene and the disease.
infection (29 papers, 2008 to 2025). The state of being infected such as from the introduction of a foreign agent such as serum, vaccine, antigenic substance or organism. "Interestingly, time course infection studies support a Tir-TRAF2 relationship as EPEC induced a dramatic loss in the levels of activation-associated multimeric TRAF2 proteins by a process dependent on Tir and Intimin." (PMID 22144899, 2011). "At the peak of infection (72 h) fifty-one genes, such as IFNβ, TRAF2, MYD88 and C7b, were exclusively up-regulated." (PMID 40906234, 2025). "Within the ubiquitin pathway, E3 ubiquitin ligases including HOIP (RNF31), TRAF2, and Pellino (PELI1) showed marked infection-dependent changes at the level of phosphorylation (e.g. RNF31_S445) and ubiquitination (e.g. PELI_K202 early, TRAF2_K313 late)." (PMID 34085925, 2021). "Over-expression of TRAF2 by Ad-TRAF2 infection in cultured isolated cardiomyocytes leads to their enhanced hypertrophy in response to Ang II treatment in vitro, whereas, decreased TRAF2 expression by Ad-shTRAF2 infection attenuated the hypertrophy." (PMID 30186311, 2018). "In the context of wild-type ORFV infection, virion-associated ORFV073 is immediately available to interfere with any potential TRAF2-induced NF-κB activation by inhibiting IKK activation possibly by interaction with NEMO." (PMID 28787456, 2017). "Compared with the untreated cells, TRAF-2 mRNA expression increased (P < 0.0001) at 24 h but decreased (P = 0.0008) at 72 h after infection with BVDV." (PMID 27617959, 2016). "Soon after infection, TRAF2−/− MEFs showed rapid and pronounced cell contractility, with almost all cells (97%) being rounded after only 1 h." (PMID 24429366, 2014). "In the TRAF2+/+ MEFs, the majority of the virions appeared to enter and uncoat within 30 min of infection, with only a small increase in the number of uncoated cores per cell being detected at between 30 min and 1 h." (PMID 24429366, 2014). "The degradation rate of IκBα in Traf2 stably expressing MEFs was higher than that of Traf2-knockout MEFs at 20 and 40 min after infection suggesting that TRAF2 plays a role in Shigella-induced NF-κB activation." (PMID 23754945, 2013). "Loss of TRAF2 expression, either through small interfering RNA treatment of HeLa cells or through genetic knockout in murine embryonic fibroblasts (MEFs), led to significant reductions in VACV growth following low-multiplicity infection." (PMID 24429366, 2014). "To identify the stage at which a deficiency of TRAF2 hinders VACV replication, we examined the timing of production of early and late VACV proteins in TRAF2+/+ and TRAF2−/− MEFs by Western blotting of cell lysates at various times following infection at a high multiplicity (MOI = 10)." (PMID 24429366, 2014). "Infection with P. gingivalis dramatically increases A20 expression in innate immune cells, which subsequently interacts with TRAF1 and TRAF2 to form a ubiquitin-editing complex to prevent K63 polyubiquitin chain synthesis by TRAF6." (PMID 35588785, 2022). "ii) TLR3, a receptor for viral dsRNA, displayed a strong reduction in influenza virus and icMERS infection, while TICAM1, TRAF1, TRAF2, TRAF3 and TRAF6, adaptors responsible for TLR3, changed in an opposite direction with TLR3." (PMID 34248940, 2021). "It would be interesting to compare the CPE seen in TRAF2−/− and JNK1/2−/− MEFs at 1 h after infection with VACV to see if similar changes are noted." (PMID 24429366, 2014). "Since XBP1 is not responsive to infection, we sought to determine if TRAF2 has a functional role during pathogen colonization." (PMID 35862781, 2022). "Early inhibition of IKK complex activation during infection, ORFV119-TRAF2 interaction in infected cells, and a proposed role for TRAF2 in poxvirus entry suggest that ORFV119 may be inhibiting ORFV entry mediated activation of NF-κB signaling." (PMID 29244863, 2017).
infection (continued). "We constructed a homozygous mutant mouse ES cell line in the Traf2 gene that is known to play a role in tumour necrosis factor-α signalling but has not been studied for its role in infections or response to Toll-like receptor agonists." (PMID 25752829, 2015). "In single-cycle infections, there was delayed production of both early and late VACV proteins as well as accelerated virus-induced alterations to cell morphology, indicating that TRAF2 influences early stages of virus replication." (PMID 24429366, 2014). "In addition to revealing the TRAF-2 and TRAF-6 ubiquitin ligase complexes, which have known roles in immune signaling during infection, this analysis identified ubiquitin ligase complexes, including CUL3, RBX1, and MDM2, that have not been previously implicated in Mtb pathogenesis." (PMID 31951200, 2020). "We investigated both of these scenarios and found that EEVs produced from TRAF2−/− cells infected TRAF2+/+ and TRAF2−/− cells equally well and that after 8 h of infection with VACV similar numbers of CEVs were present on the surface of TRAF2+/+ and TRAF2−/− cells (data not shown)." (PMID 24429366, 2014). "Six days following infection, the cells were electroporated with crRNPs in technical triplicate using either a non-targeting control guide (NTC-03) or the TRAF2/UHRF1 guide resulting in the strongest phenotype in our previous screen (TRAF2-01 and UHRF1-01)." (PMID 38411080, 2024). "We found that TRAF2, 3, and 6 but not TRAF5 showed induced interaction with MAVS, confirming that multiple TRAFs were recruited to MAVS upon infection." (PMID 29125880, 2017). "In line with a previous report, our findings suggest that PEDV may exploit kinase-dependent pathways, such as MAPK/AP-1 and JNK/p38, via TRAF2, TRAF6, and TBK1 to enhance viral replication during the acute phase of infection in weaned piglets, whereas such modulation was absent in newborn piglets." (PMID 40589734, 2025).
cardiovascular disease (3 papers, 2011 to 2025). "An examination of the literature and annotated disease databases indicates that TRAF2, SHKBP1 and UBC have not been widely investigated in the context of cardiovascular disease, and that no quantitative links have been made to clinical response after MI." (PMID 21756327, 2011).
bacterial infection (2 papers, 2019 to 2020). "Functional annotation of putatively selected genes revealed that these genes were predominantly associated with immune-related functions, inclusive of genes such as C5AR1 and MYH10 (bacterial infection); ARHGEF1, ERCC2 and TRAF2 (viral infection) and IFNGR2 (both viral and bacterial infection)." (PMID 33116287, 2020).
infectious disease (1 paper, 2014). A disorder directly resulting from the presence and activity of a microbial, viral, or parasitic agent in humans. "JAK-STAT, TRAF2/TAK1, and PI3K/AKT signaling pathways are reported to be involved in the regulation of CXCL10 in such virus infectious diseases as HIV, HBV, and influenza A." (PMID 24701034, 2014).
TRAF2 also shares sentences with these, for which no sentence is quoted: autoimmune disease (3 papers); Splenomegaly (3); acute myocardial infarction (2); dyslipidemia (2); osteosarcoma (2); periodontitis (2); rheumatoid arthritis (2); acute pancreatitis (1); age-related macular degeneration (1); anemia (1); Anorexia (1); Ascites (1); breast invasive carcinoma (1); Burkitt lymphoma (1); C. perfringens infection (1); cervical squamous cell carcinoma (1); cholangiocarcinoma (1); chronic kidney disease (1); chronic myelogenous leukemia (1); Cirrhosis (1); cystic kidneys (1); depression (1); diabetic cardiomyopathy (1); diabetic nephropathy (1); endocervical adenocarcinoma (1); endometrial cancer (1); esophageal carcinoma (1); haematological disease (1); head and neck squamous cell carcinoma (1); Hepatic steatosis (1).
A further 34 diseases each share a sentence with TRAF2 in 1 paper.